INS (insulin)
Diseases named in the same sentence as INS in open-access papers (continued):
Sharing a sentence is not in itself a finding about the gene and the disease.
Glucose intolerance (continued). "A conditional knockout of HID-1 in pancreatic β cells leads to glucose intolerance and a remarkable increase in the serum proinsulin/insulin ratio caused by defective proinsulin processing." (PMID 27751232, 2016). "NMN administration ameliorates glucose intolerance and insulin resistance in diet- and age-induced type 2 diabetic mice, and rectifies glucose-stimulated insulin secretion and glucose intolerance in NAMPT-deficient animals, by restoring NAD+ levels." (PMID 27465020, 2016). "Genetic inactivation of Ripk3 promotes increased Caspase-8-dependent adipocyte apoptosis and WAT inflammation, associated with impaired insulin signalling in WAT as the basis for glucose intolerance." (PMID 27323669, 2016). "In contrast, ND rats showed a decrease in insulin sensitivity, associated with glucose intolerance, with increasing age, thus minimizing the effects provided by the HFD." (PMID 26918024, 2016). "For example, over expression of miR-127, a Dlk1-Dio3 mat NAFLD candidate, in pancreas islet cells suppresses insulin secretion and causes glucose intolerance; additionally, miR-342 and miR-379 are upregulated in white adipose tissue of obese mice." (PMID 27135827, 2016). "We aimed to investigate associations of the dietary inflammatory index (DII) with glucose-insulin homeostasis markers, and the risk of glucose intolerance." (PMID 27869717, 2016). "Based on glucose tolerance testing and hyperinsulinemic clamps, our results showed a moderate and reproducible protective effect of Cx3cr1 deficiency on HFD-induced glucose intolerance, and enhanced hepatic insulin sensitivity." (PMID 26393344, 2015). "Mutant mice with a targeted beta cell ZnT8 deficiency display glucose-intolerance, reduced beta cell zinc accumulation and increased proinsulin levels when fed with high-fat diet, indicating the deficiency in insulin processing and secretion." (PMID 25797421, 2015). "On the one hand, ZnT8 is essential for insulin processing and secretion in response to glucose challenge thus total loss of its function causes glucose-intolerance." (PMID 25797421, 2015). "Once glucose intolerance sets in, chronic exposure to supraphysiologic concentrations of glucose over several months can lead to gradual loss of insulin gene expression." (PMID 24299156, 2014). "Next, our goal was to decipher the molecular basis underlying defective insulin secretion and glucose intolerance in Rfx6ΔBeta mice." (PMID 25497096, 2014). "A deficiency of copper results in glucose intolerance, decreased insulin response, and increased glucose response." (PMID 25162051, 2014). "The β cell-specific deletion of XBP1 in mice resulted in a modest hyperglycaemia and glucose intolerance caused by decreased insulin secretion." (PMID 24812634, 2014). "Rfx6 loss in adult β cells leads to glucose intolerance, impaired β cell glucose sensing, and defective insulin secretion." (PMID 25497096, 2014). "In an animal model, osteocalcin deficiency was associated with glucose intolerance, reduced insulin sensitivity and increased adiposity." (PMID 25310090, 2014). "Conditional inactivation of Rfx6 in adult β cells led to insulin secretion deficiency and glucose intolerance, although insulin was still produced." (PMID 25497096, 2014). "In contrast, Sfrp5 deficiency led to severe glucose intolerance and further impaired insulin-stimulated phosphorylation of Akt in adipose tissue following high-fat feeding as compared to wild-type mice." (PMID 24465779, 2014). "Recent data have indicated that hepatic ablation of Mfn2 causes glucose intolerance and deficient hepatic insulin signalling." (PMID 24663492, 2014). "Resistin also antagonizes insulin action, causing glucose intolerance, whereas elevated serum resistin levels are associated with IR." (PMID 24829591, 2014). "Breastfeeding has been associated with lower FPG and insulin, and a lower prevalence of glucose intolerance 6–9-week postpartum." (PMID 25180037, 2014).
Glucose intolerance (continued). "It has been shown that fructose-fed rats present moderate hypertension and glucose intolerance, associated with high levels of plasma insulin, cholesterol and triglycerides." (PMID 23777435, 2013). "Previous experimental studies demonstrated that potassium depletion causes glucose intolerance, which is associated with impaired insulin secretion." (PMID 23372822, 2013). "First, we showed that the CR protocol used here was able to protect from the development of pathologies associated with aging in both WT and TgTERT mice, including insulin sensitivity and glucose intolerance, as well as protection from bone loss over time." (PMID 23349740, 2013). "Animal studies have shown that Cd can cause pancreatic β-cell damage, suppress insulin secretion, increase glucose intolerance, and have diabetogenic effects." (PMID 23405080, 2013). "Further studies with a larger number of mice are necessary to clarify the underlying mechanisms of glucose intolerance in heterozygous C3H-11NSY mice, in particular the contribution of impaired insulin secretion and insulin resistance to glucose intolerance." (PMID 23671880, 2013). "In the present study, rats given ethanol at 8 g·kg−1·d−1 for 3 months had glucose intolerance and reduced insulin sensitivity in association with altered lipid regulation." (PMID 23819126, 2013). "Impairment in the Akt activation is associated with aberrant gluconeogenesis and glucose intolerance while restoration of insulin-induced Akt phosphorylation improves insulin sensitivity and glucose tolerance in the HFD-fed mice." (PMID 23326455, 2013). "The increased insulin content by vildagliptin treatment is probably due to a reduced insulin requirement in whole body caused by amelioration of glucose intolerance." (PMID 22950702, 2013). "It has been reported that glucose intolerance in GK rats is mainly caused by reduced β-cell mass and impaired glucose-induced insulin secretion in β-cell." (PMID 24106476, 2013). "With age, LPL-deficient mice were found to display glucose intolerance and decreased first-phase insulin secretion." (PMID 23186339, 2012). "The impact of steroid use in these individuals is confounded by the use of calcineurin inhibitors (particularly tacrolimus) and sirolimus which contribute to the risk of glucose intolerance possibly by suppressing insulin production." (PMID 22830041, 2012). "Glucose intolerance is associated with 1) decreased first phase insulin secretion, 2) decreased glucose disposition index, and 3) increased hepatic glucose production." (PMID 23843832, 2012). "This is in contrast to the observation of Sandu and colleagues, who reported that a high AGE diet caused a ∼ 5 fold increase in fasting insulin level and significant glucose intolerance as compared to regular AGE fed animals." (PMID 22496902, 2012). "Altogether, these results are in keeping with those of a previous study showing that OT-deficient mice exhibit glucose intolerance and decreased insulin sensitivity." (PMID 21980491, 2011). "Intensive iron chelation therapy with DFO and DFP seems to be associated with an improvement in glucose intolerance in terms of glucose and insulin secretion, particularly in patients in early stages of glucose intolerance." (PMID 20492708, 2010). "According to our findings, glucose intolerance in Terc-/- G4 animals is caused by reduced insulin secretion only, whereas insulin sensitivity was found to be unaffected." (PMID 20876939, 2010). "While one would expect differing phenotypes, increases in weight gain and adiposity, glucose intolerance, and insulin insensitivity, are observed in both AR deficient and ERα deficient mice." (PMID 19789640, 2009). "In the strain with relatively lower endogenous expression (C57BL/6J) supplementation improved insulin sensitivity and reduced gut permeability, while in the strain with higher endogenous expression (A/J) it caused hypoinsulinemia, glucose intolerance and muscle wasting." (PMID 40926119, 2025).
Glucose intolerance (continued). "For example, mice with a knockout of Atg7, an essential autophagy gene in pancreatic β-cells producing insulin, showed structural and functional defects of pancreatic β-cells, resulting in glucose intolerance and susceptibility to diabetes in the presence of metabolic stress." (PMID 40379890, 2025). "Moreover, the impaired secretion of adiponectin, an insulin-sensitizing hormone, further diminishes insulin sensitivity, increasing the risk for development of glucose intolerance and T2DM." (PMID 41542178, 2025). "In the study population, lower economic status, employment, the use of oral medication or insulin during pregnancy, polyhydramnios, elevated 2-h postprandial glucose level and physical inactivity significantly increased the risk of developing glucose intolerance among the postpartum women." (PMID 41523956, 2025). "Dietary glycine deficiency impairs insulin secretion, reduces islet mass, and worsens glucose intolerance, while overexpression of serine hydroxymethyltransferase 2 (Shmt2), a key glycine biosynthetic enzyme, increases circulating glycine, enhances insulin output, and improves glucose control." (PMID 42037784, 2025). "Additionally, Mlkl deficiency improved insulin sensitivity, whereas Ripk3 deficiency exacerbated glucose intolerance in aged mice." (PMID 39930289, 2025). "Adults that spent SBT > 10 h/day (as measured by accelerometry) exhibit higher fasting insulin levels, a higher prevalence of glucose intolerance, T2D, and a they are at higher risk of cerebrovascular accident when compared with other adults that accumulate SBT ˂ 6 h/day." (PMID 40805805, 2025). "Nonetheless, although mice with GIPR signal inhibition in the PNS do not show alterations in body weight and remain fully sensitive to weight loss induced by GIPR antagonism, these mice develop glucose intolerance with impaired glucose-induced secretion of insulin and GIP when fed a HFD." (PMID 40301583, 2025). "Also, ectopic accumulation of FFAs in the islets of Langerhans is associated with the development of disorders of insulin secretion, beta cell stress and dysfunction, which, in turn, worsens the glucose intolerance and T2D." (PMID 41614817, 2025). "Interestingly, deletion of the Hif1a gene in β-cells causes impaired insulin secretion and glucose intolerance in mice with a decreased expression of Slc2a2 (encoding GLUT2) and Gck (encoding glucokinase)." (PMID 38673770, 2024). "We then hypothesized that glucose intolerance in male mice is caused by a lowered response to insulin secretion after glucose injection." (PMID 39639385, 2024). "This suggests that deficits in glucose regulation in peripheral insulin sensitive organs may underlie the glucose intolerance observed." (PMID 37855335, 2024). "Targeted depletion of pericytes in mice through the expression of diphtheria toxin has been shown to cause a reduction in beta-cell insulin content and secretion, reduce the expression of maturity-associated beta-cell transcription factors such as MafA and Pdx1, and lead to glucose intolerance." (PMID 38612880, 2024). "However, glucose intolerance was significantly improved, associated with an increase in insulin sensitivity in YG8R mice." (PMID 39191875, 2024). "This negative correlation might be due to vitamin D deficiency causing glucose intolerance and resistance to exogenous insulin." (PMID 39015860, 2024). "The imbalance of insulin in the mother, caused by an aggravated insulin-resistant state and reduced insulin secretion, could induce glucose intolerance and lead to the development of GDM." (PMID 39885928, 2024). "While the human study offers valuable associative insights, the concurrent presence of heightened glucose intolerance, insulin secretion, and succinate response in prediabetic conditions prevents us from conclusively establishing a direct link between the succinate/SUCNR1 axis and insulin secretion." (PMID 38713514, 2024).
Glucose intolerance (continued). "Glucose intolerance and insulin sensitivity are increased in IFN-γ-deficient DIO mice." (PMID 39606781, 2024). "However, it is still plausible that DP caused glucose intolerance in part by disrupting insulin secretion, which cannot be assessed histologically." (PMID 38833523, 2024). "In fact, in animal models, it has been seen that a 3-day intervention with a KD leads to a decrease in fasting insulin levels, resulting in glucose intolerance, which may be associated with increased lipid oxidation." (PMID 37693246, 2023). "Knockout of PI3K in mice causes glucose intolerance with decreased insulin secretion." (PMID 37277555, 2023). "In rats, a deficiency in manganese results in impaired insulin secretion and glucose intolerance." (PMID 37887373, 2023). "Collectively, our findings suggest that Talin-1 deficiency reduces insulin expression mainly through inhibiting β-cell proliferation and mass which could contribute to the glucose intolerance of cKO mice." (PMID 37903776, 2023). "Thus, chronic stimulation by RELMβ leads to glucose intolerance and hyperlipidemia associated with impaired insulin signaling, and the activations of the three MAPKs are probably related to suppression of insulin signaling." (PMID 36691020, 2023). "PCSK9 deficiency reduces insulin secretion and promotes glucose intolerance." (PMID 37513689, 2023). "This is proposed to cause a reduction in muscle mass, which may limit insulin‐dependent glucose uptake and thereby exacerbate glucose intolerance." (PMID 37715520, 2023). "We speculate that glucose intolerance in the females may be partially due to impaired hypothalamic insulin signaling caused by the deletion of CLK2 in GABAergic neurons." (PMID 37635967, 2023). "Taken together, upregulation of gluconeogenic precursors and related enzymes suggests higher rates of gluconeogenesis in PHG liver which may be associated with impaired insulin sensitivity and glucose intolerance in later life." (PMID 37414142, 2023). "Interestingly, an association has been shown between increased amniotic fluid insulin concentration occurring at 14–20 weeks gestation and maternal glucose intolerance and fetal macrosomia observed postnatally." (PMID 37176607, 2023). "Since the high-fat diet (HFD) could lower insulin sensitivity and cause glucose intolerance, we wondered whether the phenotypes in F1 males caused by paternal iAs exposure could be potentiated or masked upon HFD." (PMID 37691128, 2023). "It is therefore possible that the regulation of AQP9 in LW lemurs may be linked to glucose intolerance development (as reflected by oGTT results) and linked to a possible alteration in insulin signaling." (PMID 35457071, 2022). "Using a novel approach, involving continuous intravenous infusion of sEVs with a miniosmotic pump, we demonstrate that sEVs isolated from GDM women cause glucose intolerance in pregnant mice because of its impaired ability to stimulate compensatory insulin secretion." (PMID 36239315, 2022). "Notably, their offspring presented glucose intolerance, which is caused by deficient glucose-stimulated insulin secretion from pancreatic β cells." (PMID 39872350, 2022). "The intake of meat has been associated with glucose intolerance and impaired insulin sensitivity, and may increase the risk of T2D in adults." (PMID 35743870, 2022). "In our previous study, upregulated ARG2 expression in acinar cells during aging activate p38 MAPK, which induces the release of paracrine TNF-α, resulting in the β-cell apoptosis and insufficient insulin secretion, contributing to the aging-associated glucose intolerance." (PMID 36338341, 2022). "For example, mice with KO of Atg7, an essential autophagy gene in pancreatic β-cells producing insulin, showed structural and functional defects of pancreatic β-cells, resulting in glucose intolerance and susceptibility to diabetes in the presence of metabolic stress." (PMID 35237600, 2022).
Glucose intolerance (continued). "Adult glucose intolerance is caused mainly by changes in tissue insulin sensitivity but there may also be associated defects in insulin secretion." (PMID 36230395, 2022). "Besides, insulin content and gene expression decreased and led to the disruption of insulin secretion and glucose intolerance in the mouse model with an inactivating variant of ABCC8." (PMID 34631896, 2021). "Similarly, plasma exosomes from GDM patients also induce glucose intolerance, reduce glucose-induced insulin secretion and cause poor insulin responsiveness in mouse model." (PMID 34046039, 2021). "In particular, PG levels at 30 min in an MTT may not only predict high-risk GDM requiring insulin therapy but also contribute to predicting postpartum glucose intolerance." (PMID 33776619, 2021). "However, melanophilin-mutated leaden mice show glucose intolerance and impaired glucose-stimulated insulin secretion." (PMID 34483204, 2021). "It has been postulated that changes in expression and phosphorylation of the insulin signaling intermediates precedes the development of overt IR and glucose intolerance, providing a molecular signature associated with early stages, or pre-clinical status, of disease progression." (PMID 34959870, 2021). "Consistently, elevating blood glucose levels may cause reduced peripheral insulin sensitivity and glucose intolerance." (PMID 34899339, 2021). "However, some patients were treated with insulin even if they had only one abnormal value in a 75-g OGTT result or mild glucose intolerance, making it difficult to identify high-risk GDM on the basis of OGTT results alone." (PMID 33776619, 2021). "Deficiency of Pcsk9 results in decreased insulin secretion and increased glucose intolerance." (PMID 32527043, 2020). "Hypophosphatemia can cause glucose intolerance and tissue insensitivity to insulin." (PMID 32234035, 2020). "KATP channel openers have been suggested as beneficial medication to counteract excessive hormone release in prediabetic patients as insulin hypersecretion may cause or contribute to the development of glucose intolerance and β-cell degeneration in T2DM." (PMID 33193079, 2020). "Considering the different actions on glucose intolerance between epinephrine and norepinephrine, glucose intolerance in patients with paraganglioma could be caused by increased insulin resistance mainly as the reported case." (PMID 33324347, 2020). "In long term, a KD may increase levels of cholesterol, triglycerides (dyslipidemia), and inflammation markers, associated with glucose intolerance and insufficient insulin secretion." (PMID 31406105, 2019). "Indeed, increasing age is associated also with glucose intolerance due to a reduction in insulin sensitivity and abnormal lipid profile with increased levels of triglycerides and cholesterol." (PMID 31569595, 2019). "Given that islet vasculature has been postulated to impact adult islet function, we next asked if early developmental phenotypes in VEGF-A expression and islet hyper-vascularization in Adrb2 cKO mice are causal for the later glucose intolerance and insulin secretion defects." (PMID 30303066, 2018). "Furthermore, prenatal nicotine exposure has been shown to cause glucose intolerance and impaired brain response to insulin in the offspring." (PMID 30914861, 2018). "At this stage, body weight and fed and fasting blood glucose in Akita mice were still normal; however, the mice exhibited marked β-cell dysfunction, evident by glucose intolerance associated with blunt insulin response to glucose and decreased pancreatic insulin content." (PMID 30412050, 2018). "The present results show that mice chronically exposed to a lard-based HFD develop glucose intolerance associated to reduced insulin sensitivity, impaired hippocampal-dependent spatial memory, and neurochemical alterations in the hippocampus, cortex and hypothalamus." (PMID 30670942, 2018).